GPX4 (glutathione peroxidase 4)
Diseases named in the same sentence as GPX4 in open-access papers (continued):
Sharing a sentence is not in itself a finding about the gene and the disease.
hepatocellular carcinoma (continued). "PLAG1, regulated by the lncRNA PVT1, confers resistance to sorafenib-induced ferroptosis in hepatocellular carcinoma by upregulating GPX4 and maintaining redox homeostasis." (PMID 39315094, 2024). "Research conducted by Yang and colleagues illustrated that the activation of the Nrf2/HO-1/GPX4 axis suppresses the progression of hepatocellular carcinoma through polyphyllin I induced ferroptosis." (PMID 39315094, 2024). "Solasonine also contributed to the ferroptosis of hepatocellular carcinoma cells by the destruction of the glutathione redox system with increasing lipid ROS levels as well as significantly decreasing the levels of GPX4, GSS mRNA, and protein." (PMID 39021832, 2024). "ST ethanol extract induces ferroptosis in hepatoma cells through HO-1 expression and GPX4 suppression, with enhanced efficacy when combined with lenvatinib, even in resistant cells." (PMID 39315094, 2024). "For example, inhibiting GPX4 activity has been shown to induce ferroptosis in hepatocellular carcinoma (HCC) cells, and targeting GPX4 can alleviate ferroptosis and aid in the treatment of metabolism-related fatty liver disease." (PMID 39119475, 2024). "The association between 4-HNE accumulation, as well as GPX4 and FSP1 expression, and cancer has been investigated in various cancers, including gastric cancer and hepatocellular carcinoma, and has attracted attention as a potential new therapeutic strategy." (PMID 39594843, 2024). "Subsequent experiments revealed that circ0060467 competes with AIFM2 and GPX4, thereby inhibiting cancer cell ferroptosis by binding to miR-6085 and promoting hepatocellular carcinoma progression." (PMID 38244593, 2024). "Circ_0016142 promotes hepatocellular carcinoma cell proliferation by inhibiting ferroptosis through the miR-188-3p/GPX4 axis." (PMID 39315094, 2024). "Recently, TGF‐β has been reported to induce ferroptosis by inhibiting GPX4 and cysteine transporters in hepatocellular carcinoma cells and renal tubular cells, enhancing lipid-oxidation." (PMID 37293506, 2023). "Dihydroartemisinin and sorafenib work synergistically to increase the levels of ROS and decrease the levels of proteins, including GPX4, thus, inducing ferroptosis in hepatoma cells." (PMID 37833746, 2023). "LncRNA LINC01134 recruits NRF2 to the promoter region of GPX4 to enhance GPX4 transcription, leading to the suppression of ferroptosis in hepatocellular carcinoma." (PMID 37686142, 2023). "MELK regulated the AKT/mTOR signaling pathway, causing changes in the levels of GPX4, GSH, FTH1, xCT, heme oxygenase 1(HO-1), reactive oxygen species, and Fe2+ to regulate the ferroptosis of hepatoma cells." (PMID 37008632, 2023). "For example, circRNA IL4R (circIL4R) binds to and inhibits miR-541-3p to enhance GPX4, leading to the inhibition of ferroptosis in hepatocellular carcinoma." (PMID 37686142, 2023). "In favor of this, IDH knockdown in HT-1080 fibrosarcoma and Hepa1-6 hepatoma cells promoted erastin-induced GPX4 inhibition." (PMID 35204160, 2022). "GPx4 overexpression in hepatocellular carcinoma (HC) cells and an HC animal model has been shown to inhibit cell growth, angiogenesis, and expression of the tumor proliferation marker Ki-67 18,19." (PMID 36483592, 2022). "Prior studies have noted that GPX4 is highly expressed in hepatocellular carcinoma and colon cancer and that high GPX4 expression is a poor prognostic factor in diffuse large B-cell lymphoma and lung adenocarcinoma." (PMID 36133791, 2022). "Studies have found that activation of ATF3 may regulate the expression or activity of GPX4, ultimately affecting the occurrence of ferroptosis and inhibiting the progression of hepatocellular carcinoma." (PMID 41550926, 2025). "Interestingly, solasonine, another active compound isolated from SNL, has shown similar mechanistic effects in hepatocellular carcinoma cells, promoting ferroptosis through downregulating GPX4 and GSS." (PMID 40646619, 2025).
hepatocellular carcinoma (continued). "GPX4 levels in hepatoma cells were analyzed by Western blot and RT-PCR." (PMID 39744575, 2025). "GPX7, along with GPX4, is known to be overexpressed in hepatocellular carcinoma tissues." (PMID 39684755, 2024). "Moreover, circIDE inhibits miR-19b-3p as a sponge to elevate the expression of RBMS1, which in turn reduces the stability of GPX4 mRNA to facilitate ferroptosis in hepatocellular carcinoma." (PMID 37686142, 2023). "USP14 also plays important roles in tumor death, for example, USP14 inhibits hepatocellular carcinoma apoptosis by stabilizing the GPX4 protein, and the inhibition of USP14 increases the degree of gastric cancer apoptosis, with an increased expression of cleaved caspase-3 and cleaved PARP." (PMID 37686660, 2023). "Moreover, AKT was recently shown to inhibit GPX4 degradation through creatine kinase B-dependent phosphorylation, thereby mitigating ferroptosis in hepatocellular carcinoma cell lines." (PMID 38097548, 2023). "Transmembrane protein 147 (TMEM147) upregulates DHCR7 via signal transducer and activator of transcription 2 (STAT2) in hepatocellular carcinoma (HCC), elevating 27HC and GPX4, which strengthens ferroptosis resistance and metastasis." (PMID 41596341, 2026). "Interestingly, knockdown of WTAP promoted expressions of GPX4 in hepatoma cells." (PMID 39744575, 2025). "Selenium-containing antioxidant enzymes such as glutathione peroxidase 4 (GPx4) and thioredoxin reductase 1 (TrxR1, encoded by TXNRD1) have emerged as therapeutic targets in hepatocellular carcinoma (HCC), a highly treatment-resistant cancer." (PMID 40818321, 2025). "and enhances the therapeutic impact of sorafenib in hepatocellular carcinoma (HCC) by preventing the activity of GPX4 and additional disruption of cellular glutathione levels." (PMID 39315094, 2024). "Gallic acid induces ferroptosis in hepatocellular carcinoma cells by inhibiting SLC7A11 and GPX4 expression and blocking the Wnt/β-catenin pathway, highlighting its potential as a therapeutic agent for HCC." (PMID 39315094, 2024). "At the same time, the activity of the SLC7A11/GPX4 axis, an anti-ferroptosis system in hepatocellular carcinoma cells, was also significantly inhibited by curcumin, which further exacerbated the degree of intracellular ferroptosis in hepatocellular carcinoma cells." (PMID 39311951, 2024). "Similarly, liver-specific knockout of Gpx4 accelerates diethylnitrosamine-induced hepatocellular carcinoma by releasing high-mobility group box 1 (HMGB1), recruiting myeloid-derived suppressor cells (MDSCs), and upregulating the checkpoint protein CD274 (also known as PD-L1)." (PMID 38844964, 2024). "However, the effects of the phosphorylation/dephosphorylation status of GPX4 on the regulation of inducible ferroptosis in hepatocellular carcinoma (HCC) remain unclear." (PMID 37554285, 2023). "Atractylodin was found to induce ferroptosis in hepatocellular carcinoma (HCC) cells by suppressing the expression of GPX4 and activating the ACSL4 and TFR1 proteins." (PMID 37833746, 2023). "Hence, we evaluated the susceptibility of a mouse hepatoma cell line (Hepa1-6) to oncogenic-RAS-selective lethal compound 3 (RSL3), a ferroptosis inducer that directly suppresses the anti-ferroptotic activity of GPX4." (PMID 35963845, 2022). "Furthermore, targeting GPX4 also improved the response of hepatoma cells to sorafenib." (PMID 33931597, 2021). "There is evidence that GPX4 modulates hepatocellular carcinoma (HCC) in both humans and rodent models." (PMID 30200430, 2018). "To further assess the possible role of caspase-2 in ferroptosis in liver cells, we used small interfering RNA (siRNA) to knockdown CASP2 in Huh7 hepatoma cells and then induced ferroptosis with either erastin or RSL3, a small-molecule inhibitor of GPX4." (PMID 41477850, 2026). "Ferroptosis regulation by miRNAs modulating GPX4 and SLC7A11 to either suppress or promote ferroptosis in hepatocellular carcinoma, osteosarcoma, and other cancers." (PMID 40403492, 2025).
hepatocellular carcinoma (continued). "capitata, which induces ferroptosis in hepatocellular carcinoma cells by downregulating SLC7A11 and promoting GPX4 degradation." (PMID 40790027, 2025). "Ketamine can induce ferroptosis in hepatocellular carcinoma cells in vitro and in vivo, by reducing the expression of long non-coding RNA PVT1 (lnc PVT1) and GPX4, thereby triggering ferroptosis in hepatocellular carcinoma cells." (PMID 40959280, 2025). "For instance, GPx4 overexpression can activate PTEN/PI3K/AKT signaling and promoting metastasis via transcriptionally silencing GRHL3 (Grainyhead-like 3) expression in hepatocellular carcinoma." (PMID 39908861, 2025). "In hepatocellular carcinoma, IGF2BP3 stabilizes NRF2 mRNA to inhibit ferroptosis; whereas in lung adenocarcinoma, it modulates multiple anti-ferroptotic regulators such as GPX4, SLC3A2, ACSL3, and FTH1 to confer ferroptosis resistance." (PMID 40530014, 2025). "In hepatocellular carcinoma (HCC), tumor cells exhibit increased expression of ACSL4 and transferrin receptor 1 (TfR1), as well as decreased GPX4 activity." (PMID 40733290, 2025). "To validate FSP1 as a central target of ginsenoside RK1-mediated ferroptosis in hepatocellular carcinoma, we engineered overexpression plasmids for GCH1, DHODH, GPX4, and FSP1, respectively, and transfected them into HepG2 cells." (PMID 39065721, 2024). "Glutathione reduces Fe(III) to Fe(II) in hepatocellular carcinoma, triggering ferroptosis and breaking down RF@LA-Fe-MOF to release RSL3 and iFSP1, which act as inhibitors of GPX4 and FSP1, respectively." (PMID 38738178, 2024). "For example, hepatocellular carcinoma has been reported to have a worse prognosis with lower accumulation of 4-HNE and higher expression of GPX4." (PMID 39594843, 2024). "SEH1L promotes hepatocellular carcinoma progression by inhibiting ferroptosis, while its silencing induces ferroptosis via the ATF3/HMOX1/GPX4 axis, suppressing tumor growth." (PMID 39315094, 2024). "In hepatocellular carcinoma (HCC), polyphyllin VI hinders STAT3 phosphorylation, suppresses GPX4 expression and triggers ferroptosis in HCC cells, ultimately hindering invasion and metastasis." (PMID 38205151, 2024). "It has been reported that HCG18 knockdown decreases cell proliferation, increases apoptosis, and enhances sorafenib resistance via activating ferroptosis in hepatocellular carcinoma; these effects are mediated via the HCG18/miR-450b-5p/GPX4 axis." (PMID 38778030, 2024). "The results of Western Blot showed that curcumin decreased the expression of ferroptosis-related proteins SLC7A11, GSS, GPX4, and FTH1, as well as increased the expression levels of PTGS2 and ACSL4 in hepatocellular carcinoma tissues." (PMID 39311951, 2024). "This study indicated that SEH1L siliencing could induce ferroptosis and suppresses hepatocellular carcinoma (HCC) progression via ATF3/HMOX1/GPX4 axis." (PMID 39095556, 2024). "ACP can downregulate the expression of GPX4 and SLC7A1, which can lead to ferroptosis and inhibit the growth of human hepatoma cells." (PMID 37833746, 2023). "Ferroptosis-related proteins SLC7A11 and GPX4 participate in the regulation of the growth and proliferation of some types of carcinoma cells, such as lymphocytoma, ductal cell cancer of the pancreas, and hepatocellular carcinoma (HCC)." (PMID 37807410, 2023). "Solasonine can increase ROS level, inhibit the expression of GPX4 and GSS, and promote ferroptosis of hepatoma cells." (PMID 35246010, 2022). "For example, the induction of ferroptosis in hepatocellular carcinoma cells, which has the effect of suppressing cell viability and proliferation, can be activated via the lnc-PVT1/miR-214-3p/GPX4 axis, TRIB2/β-TrCP/TFRC, or p62-Keap1-NRF2 pathways." (PMID 35615577, 2022). "To date, the main regulatory mediators mediating the ferroptotic response in Hepatocellular Carcinoma (HCC) cells have been identified as System Xc− and GPX4." (PMID 36105219, 2022).
hepatocellular carcinoma (continued). "In conclusion, TGF-β1 represses xCT expression via Smad3 activation and enhances lipid peroxidation in hepatocellular carcinoma cells with an early TGF-β1 signature, which would benefit from the targeting of GPX4." (PMID 32471991, 2020). "In a nutshell, WTAP affected NOA1 to activate the GPX4 expression and reduce the Fe2+, improving GSH/GSSH levels to suppress ferroptosis of hepatoma cells, which may promote the occurrence and development of HCC." (PMID 39744575, 2025). "Remarkably, while overexpression of GCH1, DHODH, and GPX4 failed to significantly increase cell viability in hepatocellular carcinoma cells, overexpression of FSP1 led to a substantial increase in cell viability." (PMID 39065721, 2024). "In hepatocellular carcinoma, PNO1 inhibition blocked SLC7A11 expression and the xCT activity followed cystine intake, which downregulated the accumulation of GSH and expression of GPX4 and induced ferroptosis." (PMID 37268653, 2023). "Hepatoma tissues also showed slightly lower levels of GPX4 in LDL-TO group compared to untreated controls, but the LDL-DHA treatment group experienced an even greater diminution of GPX4." (PMID 36505796, 2022). "GPX4 and GPX7 were overexpressed in the tissues of human hepatocellular carcinoma." (PMID 34531924, 2021). "Notably, overexpression of GCH1, DHODH, and GPX4 did not mitigate the heightened ferroptosis sensitivity induced by ginsenoside RK1 in hepatocellular carcinoma cells." (PMID 39065721, 2024). "However, in patients with hepatocellular carcinoma, skin melanoma, testicular germ cell tumor, uterine carcinosarcoma, there was no significance between GPX4 and OS17." (PMID 36443446, 2022). "It has been found that NRF2 can affect cell ferroptosis by regulating HO-1, GPX4, NQO1, and FTH1, which play important roles in the protection of hepatocellular carcinoma (HCC) cells from ferroptosis." (PMID 35899120, 2022). "Upregulation of GPX4, PRDX1 and CYP19A1 genes have been previously detected in biopsies of HCV infected chimpanzees or in human hepatocellular carcinoma (HCC) samples." (PMID 18793431, 2008). "GPX4 and SLC7A11 are also important in hepatocellular carcinoma (HCC)." (PMID 38590315, 2024). "Scutellaria barbata reduced GPX4 and SLC7A11 mRNA and protein levels to induce ferroptosis characterized by iron-mediated lipid peroxidation and ROS metabolism in hepatocellular carcinoma, thus suppressing HCC tumorigenicity in vivo." (PMID 39021832, 2024). "It is reported that in the prognosis model of hepatocellular carcinoma, the genes (NFS1, CISD1, ACSL3, NQO1, SLC7A11, GPX4) that can protect hepatocytes with ferroptosis and the genes (ACACA, CARS, G6PD, SLC1A5) that induce ferroptosis are all up-regulated in HCC, and are related to poor prognosis." (PMID 36387286, 2022). "In order to determine whether the LINC01134/Nrf2/GPX4 axis has clinical correlation and pathological relationship with the occurrence of HCC, we examined the expression of LINC01134 by FISH, and the expression of GPX4 and Nrf2 via IHC in a group of hepatocellular carcinoma tissues (n = 58)." (PMID 35875091, 2022).
gastric cancer (105 papers, 2015 to 2026). A primary or metastatic malignant neoplasm involving the stomach. "In conclusion, the GPX4 protein is linked to the occurrence and progression of gastric cancer, as well as gastric cancer chemodrug resistance and patient prognosis, and targeted GPX4 blockade improves gastric cancer chemosensitivity and overall survival rate." (PMID 40969276, 2025). "At the same time, high GPX4 expression was associated with a poor prognosis in gastric cancer patients." (PMID 40969276, 2025). "In contrast, lactylation mediated by the lactyltransferase NAA10 at NSUN2 (at sites K216, K389) causes a decrease in GSH levels and GPX4 activity, thereby inducing resistance to ferroptosis in gastric cancer cells." (PMID 41480383, 2025). "GPX4 upregulation is significantly associated with poor disease-specific survival and overall survival of gastric cancer patients and its silencing decreases the cell proliferation of malignant cells." (PMID 38778030, 2024). "A similar effect was observed in gastric cancer cells treated with the STAT3 inhibitor W1131 caused by reduced STAT3 occupancy on the GPX4, SLC7A11, and FTH1 promoters." (PMID 38539832, 2024). "GPX4 is lowly expressed in gastric cancer (GC) cells, making them more susceptible to ferroptosis than normal intestinal cells." (PMID 36105219, 2022). "Moreover, ferroptosis has been associated with gastric cancer progression, particularly at metastatic sites, highlighting GPX4 as a key mediator of resistance." (PMID 40846695, 2025). "It suggested that OP-B may induce ferroptosis in gastric cancer cells by inhibiting GPX4/Xc−, inducing ROS accumulation and glutathione deficiency." (PMID 38738174, 2024). "Collectively, our findings reveal a previously unrecognized role of PISD in linking mitochondrial phospholipid metabolism to STAT3/GPX4-dependent ferroptosis, providing mechanistic insights into the regulation of ferroptosis in gastric cancer." (PMID 41899452, 2026). "This study reveals that OTUD5, a deubiquitinating enzyme, is a key regulator of GPX4 in gastric cancer cells." (PMID 40070026, 2025). "Functional experiments within colorectal and gastric cancer cell lines demonstrated that increased GPX4 levels boosted cellular proliferation, suggesting an oncogenic role for GPX4, a finding that aligns with previous researches." (PMID 41142608, 2025). "Recent studies demonstrate that NAA10-mediated lactylation of NSUN2 at residues K216 and K389 depletes glutathione levels and compromises GPX4 activity, thereby conferring resistance to ferroptosis in gastric cancer cells." (PMID 41480383, 2025). "CST1 inhibits ferroptosis and promotes gastric cancer metastasis by regulating GPX4 protein stability." (PMID 40136465, 2025). "We further confirmed the reduction in kynurenine amounts and lower kynurenine/tryptophan (Kyn/Trp) ratios in both the supernatants and lysates of GPX4-knockdown gastric cancer cells." (PMID 40365295, 2025). "Recent studies show that the Wnt signaling pathway reduces lipid peroxidation by up-regulating GPX4, an essential antioxidant enzyme that prevents cellular iron oxidation, ultimately inhibiting ferroptosis in gastric cancer cells." (PMID 41048937, 2025). "Fresh gastric cancer samples from 26 patients at Zhejiang Cancer Hospital were collected, and GPX4 expression and the metabolic levels of kynurenine and tryptophan in the corresponding tissues were analyzed." (PMID 40365295, 2025). "The cysteine protease inhibitor SN has been shown to recruit members of the ovarian tumor domain-containing cysteine protease superfamily, reduce GPX4 ubiquitination, lower ROS levels, and inhibit ferroptosis in gastric cancer cells." (PMID 40156957, 2025).